SNHG26 (small nucleolar RNA host gene 26)
Synonyms: AC005682.5
Gene: Long non-coding RNA gene on chromosome 7 (22,853,869 to 22,913,785, forward strand). Ensembl gene ENSG00000228649.
Gene Ontology:
Biological process: RNA processing
Cellular component: nucleolus
Diseases named in the same sentence as SNHG26 in open-access papers:
SNHG26 is named in the same sentence as 13 diseases in open-access papers, as found by Europe PMC text mining. Sharing a sentence is not in itself a finding about the gene and the disease. The quoted sentences say what the papers report.
bladder cancer (2 papers, 2022 to 2023). "Wang Y. and Tong H. showed that SNHG26 is closely associated with the tumour, immune microenvironment, CC, and bladder cancer." (PMID 35087586, 2022). "In bladder cancer, SNHG26 was discovered to be an epithelial-mesenchymal transition-related prognostic factor." (PMID 37396046, 2023).
gastric cancer (2 papers, 2024 to 2025). A primary or metastatic malignant neoplasm involving the stomach. "To investigate the biological function of SNHG26 in GC, we first detected the RNA level of SNHG26 in different gastric cancer cell lines." (PMID 38553452, 2024).
tongue squamous cell carcinoma (2 papers, 2022 to 2023). A squamous cell carcinoma that arises from the tongue. "In tongue squamous cell carcinoma (TSCC) cells, SNHG26 directly binds to the PGK1 protein, inhibiting its ubiquitination and activating the Akt/mTOR signalling pathway." (PMID 37723547, 2023).
bladder urothelial carcinoma (1 paper, 2021). "For example, SNHG26 has significantly upregulated in bladder urothelial carcinoma and associated with poor survival." (PMID 34290738, 2021).
diabetic foot ulcers (1 paper, 2024). "Moreover, SNHG26 expression was reduced in human diabetic foot ulcers and diabetic mouse wounds compared to acute wounds, highlighting its relevance in wound healing and chronic wound pathology." (PMID 39366968, 2024).
glioma (1 paper, 2023). A benign or malignant brain and spinal cord tumor that arises from glial cells (astrocytes, oligodendrocytes, ependymal cells). "We tested SNHG26’s role in the human glioma cell line, U251." (PMID 37567476, 2023).
cancer (7 papers, 2021 to 2025). A tumor composed of atypical neoplastic, often pleomorphic cells that invade other tissues. "Another lncRNAs in this TIILncSig, SNHG26, have also been associated with carcinogenesis and clinical outcome in several cancers." (PMID 34290738, 2021). "Small nucleolar RNA host gene 26 (SNHG26), a recently identified lncRNA, has been reported to be aberrantly expressed in various human cancers." (PMID 41310877, 2025). "SNHG26 overexpression in cancer cells significantly reduced CD8+ T cell apoptosis from approximately 25% to 10% in co‐cultures with HCT116 cells and from 30% to 15% in co‐cultures with SW480 cells." (PMID 41310877, 2025). "Preliminary studies have suggested that SNHG26 may participate in cancer cell proliferation and metastasis, but the precise molecular pathways through which SNHG26 exerts its functions in CRC are not well defined." (PMID 41310877, 2025). "Given the emerging role of cuproptosis in cancer therapeutic strategies and the relationship between SNHG26 and cuproptosis in CRC, we investigated whether SNHG26 modulates the sensitivity of CRC cells to this novel cell death pathway." (PMID 41310877, 2025). "However, the biological function of SNHG26 in cancer remains largely unknown." (PMID 38553452, 2024). "In the present study, combined with RNA pull-down and RIP assays, we found that SNHG26 could interact with NCL, a nucleocytoplasmic RNA-binding protein that plays multiple roles in cancer." (PMID 38553452, 2024). "SNHG26 is also known as small nucleolar RNA host gene 26 (SNHG26), which belongs to a group of lncRNAs called small nucleolar RNA host genes (SNHGs) that are often found upregulated in cancers, and that have oncogenic functions connected to proliferation and cell cycle progression." (PMID 34556693, 2021).
tumor (5 papers, 2022 to 2025). "Recent studies have implicated lncRNAs in modulating tumour‐immune interactions, but the potential role of SNHG26 in regulating the immune microenvironment in CRC has not been investigated." (PMID 41310877, 2025). "Tumors in the SNHG26 overexpression group were larger than those in the control group, indicating that SNHG26 could promote tumor growth." (PMID 38553452, 2024). "Moreover, RNA FISH of the GC cell lines HGC-27 and MKN-28, GC tumor and adjacent nontumor tissues, and the subcellular fractionation of HGC-27 suggested that SNHG26 was mainly distributed in the nucleus." (PMID 38553452, 2024).
SNHG26 also shares sentences with these, for which no sentence is quoted: cervical cancer (1 paper); colorectal (1); colorectal cancer (1); glioblastoma (1); prostate carcinoma (1).